GNB5 (G protein subunit beta 5)
Diseases named in the same sentence as GNB5 in open-access papers (continued):
Sharing a sentence is not in itself a finding about the gene and the disease.
lymphoma (1 paper, 2024). A malignant (clonal) proliferation of B- lymphocytes or T- lymphocytes which involves the lymph nodes, bone marrow and/or extranodal sites. "In this study, key genes from the chemokine signaling pathway—HCK, GNB5, NRAS, and VAV2—were validated, confirming their differential expression between LGBLEL and lymphoma and suggesting their important role in the malignant transformation of LGBLEL." (PMID 39451532, 2024). "RT-qPCR showed that, compared to the lymphoma group, the LGBLEL group had significantly higher expression of CCL28, CXCL17, HCK, GNB5, NRAS, and VAV2 (p = 0.001, <0.001, <0.001, <0.001, =0.020, <0.001, respectively) and lower expression of CCR1 (p = 0.002)." (PMID 39451532, 2024). "WB revealed that, compared to the lymphoma group, the LGBLEL group exhibited significantly higher expression of CCL28, CXCL17, HCK, GNB5, NRAS, and VAV2 (p = 0.012, 0.005, 0.009, 0.011, 0.008, and 0.003, respectively) and lower expression of CCR1 (p = 0.014)." (PMID 39451532, 2024). "Compared to the lymphoma group, the protein quantitative analysis of the LGBLEL group exhibited significantly differentially expressed CCL28, CCR1, CXCL17, HCK, GNB5, NRAS, and VAV2 (p = 0.003, 0.011, 0.001, 0.024, 0.005, 0.019, and 0.031, respectively)." (PMID 39451532, 2024). "Compared to the lymphoma group, the LGBLEL group exhibited higher expression levels of CCL28, CXCL17, HCK, GNB5, NRAS, and VAV2 (p = 0.001, <0.001, <0.001, <0.001, 0.020, and <0.001, respectively) and lower expression of CCR1 (p = 0.002)." (PMID 39451532, 2024). "Compared to the lymphoma group, the LGBLEL group showed higher expression of CCL28, CXCL17, HCK, GNB5, NRAS, and VAV2 (p = 0.012, 0.005, 0.009, 0.011, 0.008, and 0.003, respectively) and lower expression of CCR1 (p = 0.014)." (PMID 39451532, 2024).
Nystagmus (1 paper, 2017). Rhythmic, involuntary oscillations of one or both eyes related to abnormality in fixation, conjugate gaze, or vestibular mechanisms. "A homozygous splice site variant (c.249 + 3 A > G) in GNB5 was detected in two affected siblings from the clinical diagnostic laboratory exhibiting DD/ID, nystagmus, and sinus node dysfunction." (PMID 28327206, 2017).
pulpitis (1 paper, 2023). Inflammation of the dental pulp. "Amongst the 22 modules, the darkgray module was determined as the most pivotal module for pulpitis, from which 5 core genes, A HMOX1, LOX, ACTG1, STAT3 and GNB5, were selected, and assumed to exert pivotal effects on the pathophysiologic causal links of pulpitis." (PMID 36593446, 2023). "More in depth researches are needed to interrogate the effects of ACTG1 and GNB5 on pulpitis." (PMID 36593446, 2023). "Therefore, the role of STAT3 and GNB5 in pulpitis and material modification to regulate these two genes should be further investigated." (PMID 36593446, 2023). "Subsequently, the protein coding genes HMOX1, LOX, ACTG1, STAT3, GNB5 were selected as the core genes, as they were most negatively or positively correlated modules with pulpitis statistically." (PMID 36593446, 2023). "However, in our study, the levels of STAT3 and GNB5 were not reversed, and these two genes were less studied in pulpitis." (PMID 36593446, 2023). "However, to our knowledge ACTG1 and GNB5 have not been studied in pulpitis yet." (PMID 36593446, 2023).
cancer (6 papers, 2019 to 2025). A tumor composed of atypical neoplastic, often pleomorphic cells that invade other tissues. "For example, the following top 100 MDS genes can be mentioned that are not yet covered by approved or experimental cancer or antineoplastic drugs [according to DrugBank, DGIdb, FDA6, HMDB, Tocris7, GeneCards databases]: GRB2, SOS1,SOS2, SHC1, GNB1, CREB1, GNG2, GNAQ, GNB5, GNAI2." (PMID 30728774, 2019).
neurodevelopmental disorder (6 papers, 2021 to 2025). A behavioral and cognitive disorder with onset during the developmental period that involves impaired or aberrant development of intellectual, motor, or social functions. "All subjects were found to have variants in GNB5 and presented with a similar rare phenotype, which was later named GNB5-related neurodevelopmental disorder." (PMID 40565581, 2025). "Polymorphisms or mutations in GNB1, GNB2, and GNB5 genes were reported to be associated with neurodevelopmental disorders." (PMID 36077181, 2022). "In addition, other mutations in GNB2 and GNB5 are observed in patients with neurodevelopmental disorders." (PMID 36648066, 2023).
tumor (3 papers, 2016 to 2019). "No significant changes in the expression levels of GNB5 and KCNMA1 were observed between HCC tissues and the paired non-tumor tissues, which was not consistent with meta-analysis." (PMID 27769251, 2016).
neurological disorders (2 papers, 2024 to 2025). "Gnb5 is predominantly expressed in neurons and plays an important role in various intracellular signaling processes, with emerging evidence linking it to the pathogenesis of multiple neurological disorders." (PMID 40587559, 2025).
genetic disorders (1 paper, 2021). "Overall, BRET assay may be used for drug screening in rare genetic disorders such as GNB5, where personalized therapeutics may be the only avenue." (PMID 34573334, 2021).
GNB5 also shares sentences with these, for which no sentence is quoted: language delay (4 papers); Arrhythmia (2); developmental delay (2); glioma (2); infection (2); asthma (1); autism (1); breast carcinoma (1); bronchopneumonia (1); cardiac arrest (1); cervical cancer (1); cognitive decline (1); colon cancer (1); COVID-19 (1); Crohn disease (1); dementia (1); depression (1); developmental and epileptic encephalopathy (1); embryonal carcinoma (1); lung carcinoma (1); microcephaly (1); Motor delay (1); Obesity (1); osteoporosis (1); osteosarcoma (1); placental insufficiency (1); Retinal dystrophy (1); retinopathy (1); schizophrenia (1); seminoma (1).
A further 6 diseases each share a sentence with GNB5 in 1 paper.